IL1B (interleukin 1 beta)
Diseases named in the same sentence as IL1B in open-access papers (continued):
Sharing a sentence is not in itself a finding about the gene and the disease.
autoinflammatory syndrome (continued). "Given the key role of IL-1β in inflammatory and autoinflammatory disorders, several IL-1 inhibitors have been developed and evaluated especially in life-threatening autoinflammatory syndromes." (PMID 28588486, 2017). "The inclusion of simvastatin in LPS-treated monocytic cultures mimics the IL-1β hypersecretion phenotype seen in the autoinflammatory syndrome MKD (18, –, 22)." (PMID 24356959, 2014). "The overproduction of IL-1β is responsible for a variety of autoinflammatory syndromes including FMF." (PMID 23437051, 2013). "Additionally, the inappropriate release of IL-1β and IL-18 has been demonstrated to elicit urticaria in autoinflammatory syndromes." (PMID 38539560, 2024). "In our model, serum IL-1β levels increased in hIL-1α cTg mice, suggesting that IL-1α stimulates inflammasome activation, and our model recapitulates, at least in part, human auto-inflammatory syndrome." (PMID 30361689, 2018). "However, mutations in the MEFV gene (that codify for pyrin) are associated with two clinically different autoinflammatory syndromes: FMF and PAAND; in both diseases, mutated pyrin associates with high serum IL-1β levels during febrile episodes." (PMID 28191008, 2017). "IL-1β plays an important role in all autoinflammatory syndromes including PFAPA." (PMID 25821352, 2015). "IL-1β is central to the pathogenesis of hereditary autoinflammatory syndromes, and while inhibition is therapeutic, abrupt suppression may disrupt homeostatic immune signaling in genetically predisposed individuals, potentially unmasking or exacerbating underlying genetic susceptibilities." (PMID 41471316, 2025). "From them, the cytokine IL-1β is one of the most prominent and critical products of inflammasome activation, since it is a key regulator of the inflammatory response and is the most important current target of therapeutic treatments for autoinflammatory syndromes." (PMID 28191008, 2017). "CAPS is a common name for three autoinflammatory syndromes (familial cold autoinflammatory syndrome, Muckle-Wells syndrome, and NOMID), in which dysregulated inflammasome results in IL-1β activation and secretion and a broad inflammation occurs." (PMID 28083070, 2016). "The overproduction of IL-1β, induced by NLRP3 inflammasome activation, is responsible for a variety of autoinflammatory syndrome including FMF." (PMID 23437051, 2013).
vitiligo (44 papers, 2011 to 2026). Generalized well circumscribed patches of leukoderma that are generally distributed over symmetric body locations and is due to autoimmune destruction of melanocytes. "Candidate gene studies highlight the role of autoimmunity in vitiligo, as polymorphisms in IL1B, IL4, PSMB8, NLRP1, NPY, FOXP3, and IFNG genes were found to be associated with vitiligo." (PMID 36164321, 2022). "Increases in IL-1β expression and genetic variation in the IL-1β gene has been linked to the likelihood of developing vitiligo." (PMID 35418942, 2022). "Recently, we have reported the association of NPY and IL1B polymorphisms with vitiligo susceptibility in Gujarat population." (PMID 27749914, 2016). "Association studies for NPY gene exon 2 (+1128 T/C), promoter (−399 T/C) and IL1B gene promoter (−511 C/T) polymorphisms in generalized and localized vitiligo patients from Gujarat." (PMID 25221996, 2014). "For the first time we report an association between IL1B promoter polymorphism and vitiligo along with higher transcript levels of IL1B in vitiligo patients as compared to controls." (PMID 25221996, 2014). "Association studies for NPY gene exon 2 (+1128 T/C), promoter (−399 T/C) and IL1B gene promoter (−511 C/T) polymorphisms in Gujarat vitiligo patients and unaffected controls." (PMID 25221996, 2014). "The genotype and allele frequencies for −511 C/T promoter polymorphism of IL1B differed significantly between vitiligo patients and controls (p<0.0001; p<0.0001 respectively)." (PMID 25221996, 2014). "Association studies for NPY gene exon 2 (+1128 T/C), promoter (−399 T/C) and IL1B gene promoter (−511 C/T) polymorphisms in active and stable vitiligo patients from Gujarat." (PMID 25221996, 2014). "Our results showed that the genotype and allele frequencies for -511C/T promoter polymorphism of IL1B differed significantly in active and stable vitiligo patients, suggesting association of this polymorphism with the disease progression." (PMID 25221996, 2014). "In the present study, we show that −511C/T promoter polymorphism of IL1B gene is associated with vitiligo in Gujarat population." (PMID 25221996, 2014). "Our results suggest that NPY −399T/C, +1128T/C and IL1B −511C/T polymorphisms are associated with vitiligo and IL1B −511C/T SNP influences its transcript levels leading to increased risk for vitiligo in Gujarat population." (PMID 25221996, 2014). "IL1B−511C/T SNP upregulates IL-1β transcript levels and results in increased risk for vitiligo." (PMID 35721084, 2022). "Taken together, altered IL1B transcript levels due to genetic variability in IL1B might be associated with elevated NPY levels in patients with vitiligo." (PMID 25221996, 2014). "Similarly, higher IL1B levels can cause autoimmune responses against melanocytes, by initiating a cascade of reactions involving inflammosome formation and ultimately resulting in vitiligo." (PMID 25221996, 2014). "In conclusion, our findings suggest that NPY exon 2 +1128 T/C, −399 T/C and IL1B −511 C/T promoter polymorphisms are significantly associated with vitiligo susceptibility, which might result in higher levels of IL1B thereby leading to autoimmune mediated responses in vitiligo." (PMID 25221996, 2014). "As our study showed high levels of serum IL‐1β and IL‐18 in vitiligo patients, activated dendritic cells in this disease can produce IL‐1β and IL‐18 in response to inflammatory stimuli." (PMID 39313936, 2024). "Unpaired t‐test analysis showed significantly higher blood levels of IL‐1β and IL‐8 in vitiligo patients compared to healthy subjects (Pv < 0.0001)." (PMID 39313936, 2024). "NLRP1 and IL-1β protein expression was strongly positive in perilesional skin of vitiligo patients with disease progression, particularly in the entire epidermis, compared to skin of healthy controls." (PMID 37325658, 2023).
vitiligo (continued). "Overexpression of the gene encoding the receptor NLRP1 (Langerhans cells) leads to the activation of inflammasome and induces the conversion of pro-IL-1β into active IL-1β, which is involved in the pathogenesis and progression of vitiligo." (PMID 37298700, 2023). "NLRP3 expression has been elevated in perilesional vitiligo skin, which correlates with increased cutaneous IL-1β expression and disease severity." (PMID 36920542, 2023). "Serum levels of NPY, MCH, ACTH, IFN-γ, CXCL10, IL-1β in patients with vitiligo of active (n = 10) and stable (n = 20) phases in both the intervention and control groups." (PMID 35721084, 2022). "The perilesional skin of vitiligo, where the disease is most active, shows an increase in IL1β, suggesting that this pathway is also involved in vitiligo progression." (PMID 35643735, 2022). "In our previous study, we have demonstrated increased serum IL-1β levels in patients with vitiligo and correlated it with disease activity and severity, as well as a decrease after routine care." (PMID 35721084, 2022). "IFN-γ, CXCL10, and IL-1β have emerged as dependable serum markers and play a critical role in T-cell response in vitiligo." (PMID 35721084, 2022). "Genetic mutations in NLRP1 have been associated with hyperplasia and skin autoimmune disease like vitiligo accompanied with high levels of IL-1β and IL-18 detected in the serum of patients." (PMID 35428946, 2022). "Oxidative stress promotes the expression of NLRP3 and downstream cytokine IL-1β in keratinocytes of patients with vitiligo." (PMID 34768860, 2021). "NLRP1 has been found to be strongly positive in progressing margins of vitiligo and NLRP1 and IL-1β are significantly associated with progressive disease rather than stable vitiligo." (PMID 34768860, 2021). "In the skin during progressive vitiligo, IL-1β is increased with activation of NOD-like receptor family pyrin domain containing 3 (NLRP3) inflammasomes." (PMID 34638746, 2021). "The study has demonstrated the correlations between increased IL-1β serum levels and the extent of vitiligo (VASI) and also the duration of disease in NSV patients." (PMID 32832001, 2020). "We found that Corynebacterium 1, Ruminococcus 2, Jeotgalibaca and Psychrobacter were correlated significantly with disease duration and serum IL-1β level in vitiligo patients." (PMID 33381090, 2020). "IL-1β, a comparatively sensitive serological marker in vitiligo progression, was negatively correlated with Corynebacterium1, Jeotgalibaca, and Psychrobacter (adjusted P < 0.1)." (PMID 33381090, 2020). "Recent studies have demonstrated that serum level of soluble interleukin (IL)-2 receptor a (CD25) reflects T-cell activation in vitiligo, whereas IL-17-induced secretion of IL-1β from keratinocytes links with autophagic melanocytes apoptosis." (PMID 33381090, 2020). "IL-1β level in serum is elevated in patients with vitiligo, and NLRP1 and IL-1β in vitiligo skin are significantly associated with the progression." (PMID 32922182, 2020). "Meanwhile, the important clue is that IL-1β, which is closely related to vitiligo activity, not only participates in the modulation of immune programs, but also enhances local antimicrobial peptides to potentiate microbiome remodeling." (PMID 33381090, 2020). "To check for the possible signs of systemic inflammation, we measured the concentration of inflammation-associated cytokines (TNF-α, IFN-γ, IL-1b, IL-1Ra, IL-2, IL-5, IL-6, CXCL8, CXCL10, G-CSF, and GM-CSF) in the plasma of vitiligo patients." (PMID 30515176, 2018). "Upregulation of IL-1β transcript in patients advocates its possible role in autoimmune pathogenesis of vitiligo." (PMID 29312598, 2017). "PSMB8 polymorphism in addition to previously reported susceptibility loci such TNFA, TNFB, IL1B, IFNG, NALP1, IL4 etc. demonstrate immunogenetic predisposition in vitiligo patients from Gujarat." (PMID 28700671, 2017).
vitiligo (continued). "It has been reported that the mRNA levels of IL-1β in vitiligo patients were found to be significantly higher than controls suggesting its possible role in inflammatory pathogenesis of vitiligo." (PMID 29312598, 2017). "We found significant difference in IL1B transcript levels between vitiligo patients and controls (Odds ratio = 0.574, Chi-square = 28.67, p = 8.588e-08) with respect to different genotypes." (PMID 25221996, 2014). "The IL1B transcript levels in vitiligo patients were significantly higher than in controls (p = 0.003) as suggested by mean ΔCp values." (PMID 25221996, 2014). "Transcript levels of IL1B were significantly higher, in patients compared to controls (p = 0.0029), in patients with active than stable vitiligo (p = 0.015), also in female patients than male patients (p = 0.026)." (PMID 25221996, 2014). "Expression of IL1B transcripts was analyzed with respect to gender differences in 37 male patients and 58 female patients with vitiligo." (PMID 25221996, 2014). "The female patients showed significant increase in IL1B mRNA levels as compared to male vitiligo patients (p = 0.026)." (PMID 25221996, 2014). "The IL1B transcript levels were compared in 95 vitiligo patients and 105 age matched unaffected controls after normalization with GAPDH transcript levels." (PMID 25221996, 2014). "The transcript levels of IL1B were analyzed with respect to progression of disease in 71 patients with active vitiligo and 24 patients with stable vitiligo." (PMID 25221996, 2014). "Up-regulation of IL1B transcript in patients advocates its possible role in autoimmune pathogenesis of vitiligo." (PMID 25221996, 2014). "Relation between percentage of vitiligo (%) with (A) IL‐1β and IL‐18, (B) TOS, and MDA." (PMID 39313936, 2024). "Serum IL-1β and serum IL-6 (vitiligo > AA) are also elevated in both diseases, supporting the hypothesis that oxidative stress is associated with the promotion and amplification of inflammatory process in both AA and vitiligo." (PMID 38673994, 2024). "However, our study showed increased levels of oxidative stress as well as IL‐1β and IL‐18 in vitiligo patients after using MBEHQ cream." (PMID 39313936, 2024). "As IL‐1β and IL‐18 are pro‐inflammatory cytokines in the autoimmune response in vitiligo, their increased blood levels after MBEHQ cream application may be due to increased ROS." (PMID 39313936, 2024). "Increased IL-1β levels were observed in the sera of active-vitiligo patients, suggesting that IL-1β may play a role in dysregulating melanocytic activity in lesional skin." (PMID 39201060, 2024). "Regarding the NLRP3 inflammasome, both protein and mRNA concentrations of NLRP3 and IL-1β were found increased in perilesional epidermal samples of vitiligo patients with progressive disease compared to healthy controls and vitiligo patients with stable disease." (PMID 37325658, 2023). "Moreover, IL-1β serum concentrations are increased in vitiligo patients with progressive disease compared to vitiligo patients with stable disease and healthy controls and positively correlated with the severity of disease progression." (PMID 37325658, 2023). "Moreover, IL-1β can induce biosynthesis and release of NPY; in turn, NPY can be involved in the humoral immune mechanism leading to a higher level of IL-1β in vitiligo." (PMID 35721084, 2022). "Moreover, the significant changes in the NPY, MCH, ACTH, IFN-γ, CXCL10 and IL-1β serum levels induced by camouflage and psychotherapy in the patients with vitiligo indicated the mechanism of psycho-neuro-endocrine-immuno-skin interaction." (PMID 35721084, 2022). "Moreover, there is an increase in proinflammatory cytokines, characteristic of innate immunity, in both serum and skin of patients with vitiligo, such as IL1α, IL1β, IL6, IL8, IL12, IL15, and TNFα." (PMID 35643735, 2022).
vitiligo (continued). "Intriguingly, of the mentioned cytokines and chemokines, many are reported to be biomarkers for vitiligo like IL‐1β, CXCL9, CXCL10, and CXCL16, which might aid vitiligo diagnosis and prognosis." (PMID 33200838, 2021). "In particular, upregulated IL-1β in the skin and sera were found in the active progression of vitiligo and could play a central role in the cutaneous T cell response in vitiligo." (PMID 34638746, 2021). "In addition, our previous study illustrated that the expression of NLRP3 and downstream cytokine of IL-1β is upregulated in peripheral keratinocytes of vitiligo." (PMID 32754591, 2020). "As a result, 10.9% of microbial variance in vitiligo could be explained by IL-1β [False Discovery Rate (FDR) = 0.005], and 6.4% by VES (FDR = 0.049)." (PMID 33381090, 2020). "Our results collectively indicated that IL-22 may potentiate IL-1β-mediated skin inflammation and result in participating in the inflammatory pathogenesis of vitiligo." (PMID 29312598, 2017). "IL-1β mRNA expression was elevated in the lesioned edge of vitiligo." (PMID 29312598, 2017). "Furthermore, Cochran-Armitage trend analysis demonstrated significant increase in IL1B transcript levels in vitiligo patients with respect to the different genotypes compared to those of controls (p = 8.588e-08)." (PMID 25221996, 2014). "In addition, the study also emphasizes the influence of NPY and IL1B genes on disease progression for developing vitiligo." (PMID 25221996, 2014). "Interestingly, the mRNA levels of IL1B in patients were found to be significantly higher than controls suggesting the possible involvement of IL1B in vitiligo pathogenesis." (PMID 25221996, 2014). "In addition, our results also demonstrated increased IL1B mRNA levels in active vitiligo as compared to stable cases, further confirming the important role of IL1B in disease progression." (PMID 25221996, 2014). "Thus, we hypothesize that increased CIRP might stimulate the activation of NLRP3 inflammasome that subsequently induce IL-1β involved in vitiligo pathogenesis." (PMID 36920542, 2023). "Therefore, IL1β inhibition can also be seen as a potential therapeutic target in vitiligo." (PMID 35643735, 2022). "Therefore, NR-046211.1 may regulate the pathogenesis of vitiligo through NR-046211.1/mir-328/IL1β axis, but NR-046211.1/mir-637/IL16, and NR-046211.1/mir-637/IL34 axis need further confirmation." (PMID 34941177, 2021). "Hence, we hypothesized that under the oxidative stress, TR could impede the production of IL-1β in keratinocytes and further abolish the detrimental effects of IL-1β on melanocytes in vitiligo." (PMID 32754591, 2020). "In addition, NLRP1 and IL-1β levels in the skin may represent better markers than detection of lymphocyte infiltration to monitor vitiligo activity." (PMID 32528469, 2020). "Thus, the directly inhibiting NLRP3 inflammasome might be a better choice than targeting IL-1β for vitiligo treatment." (PMID 32754591, 2020). "Interestingly, our recent study shows significant association of NLRP1 promoter variants with GV and NLRP1 overexpression in patients compared to controls; which might lead to increased IL1B production in vitiligo patients." (PMID 25221996, 2014). "Interestingly, our recent study suggests increased levels of SOD2 transcripts and SOD2 activity in vitiligo patients which might be one of the consequences of increased IL1B." (PMID 25221996, 2014). "Patients with vitiligo presented higher circulating levels of IFN-λ1 and IL-1b and ratios of IFN-λ1/IL-10 and IL-6/IL-10 (p < 0.05, p < 0.05, p < 0.001, and p < 0.01, respectively)." (PMID 42052095, 2026). "These aldehydes also activate immune responses by functioning as DAMPs, stimulating dendritic cells and inducing pro-inflammatory cytokines such as IL-6, IL-1β, and TNF-α, contributing to vitiligo’s autoimmune component." (PMID 40427437, 2025).